BCL2 (BCL2 apoptosis regulator)
Diseases named in the same sentence as BCL2 in open-access papers (continued):
Sharing a sentence is not in itself a finding about the gene and the disease.
cancer (continued). "Bcl-2 and Bcl-xL are critical regulators of apoptosis that are overexpressed in a variety of human cancers and pharmacological inhibition of Bcl-2 and Bcl-xL represents a promising strategy for cancer treatment." (PMID 24901320, 2014). "A growing body of evidence suggests that three anti-apoptotic proteins, i.e., survivin, Mcl-1, and Bcl-2, may be directly related to drug resistance in cancer." (PMID 24586249, 2014). "Earlier investigators have shown that plants (Glycyrrhiza uralensis Fisch) may have chemopreventive effects against different types of cancer by modulating the expression of the Bcl-2/Bax apoptotic regulatory factors." (PMID 24959190, 2014). "Anti-apoptotic B cell-chronic lymphocytic leukemia/lymphoma 2 (Bcl-2) family members (Bcl-2, Bcl-XL, Bcl-w, Bcl-b, A1/Bfl-1, and Mcl-1) are overexpressed in many cancers and inhibit apoptosis by sequestering pro-apoptotic members of the family (BH3-only proteins, and Bax and Bak)." (PMID 25285531, 2014). "bcl2 protein was decreased in cancer cells treated by all compounds at 1/4 of CC50 values." (PMID 25548920, 2014). "And Bcl-2 was decreased in CS-inhibited cancer cells (P<0.01)." (PMID 25545012, 2014). "Bcl-2 protein expression in UM-SCC-17B cancer cells was inhibited by 30% after treatment for 72 h." (PMID 25229941, 2014). "Antiapoptotic Bcl-2 protein is downregulated by the action of EOs on the cancer cells." (PMID 25003106, 2014). "Given the difference in apparent binding affinity, however, we hypothesized that in cancer cells overexpressing Bcl-2 proteins, especially those addicted to Mcl-1, Mcl-1/VDAC interactions would dominate." (PMID 25341036, 2014). "BCL2-proteins are one of the most prominent antiapoptotic proteins deregulated in cancer." (PMID 26556430, 2014). "Moreover, the pre-treatment with ADP promoted Bcl-2 down-regulation induced by cisplatin, a strong and widely used cancer chemotherapy drug, in both HUVEC and THP1." (PMID 25290311, 2014). "Bcl-2 is an anti-apoptotic protein that is frequently overexpressed in cancer." (PMID 24971890, 2014). "However, many cancers with overexpression of Bcl-2 exhibit a resistance to mitochondrial apoptotic cell death." (PMID 23483560, 2013). "Hence, this is the first study to reveal a prominent role for the type of IP3R isoform as a determinant for the sensitivity to cell death in Bcl-2-dependent cancer cell lines." (PMID 23681227, 2013). "In cancer, for example, cellular variation in anti-apoptotic protein levels (such as the Bcl2 concentration) as well as effective low number of molecules generated by over-expressed apoptotic inhibitors contribute to large cell-to-cell variability in apoptotic activation." (PMID 24709706, 2013). "Our findings highlight the importance of targeting Bcl-2's BH4 domain in Bcl-2-dependent cancers." (PMID 23681227, 2013). "Cancer cells survival requires the inhibition of apoptosis, which is accomplished by suppressing the expression of proapoptotic proteins (Bax) as well as promoting the expression of antiapoptotic proteins (Bcl-2)." (PMID 23690850, 2013). "Consequently, targeting of antiapoptotic Bcl-2 proteins is considered to provide a promising approach for chemosensitization of human cancers." (PMID 23420072, 2013).
cancer (continued). "NSAIDs such as aspirin and indomethacin have long been shown to induce cancer cell apoptosis by upregulating the expression of proapoptotic Bcl-2 proteins, such as Bax and Bak, and by downregulating expression of anti-apoptotic Bcl-2 proteins such as Bcl-2 and Bcl-XL." (PMID 23983899, 2013). "Such a chemotherapeutic strategy might work for resistant cancer cells equipped with high Bcl2 to Bax ratio but also having increased sensitivity to death receptor activation." (PMID 24709706, 2013). "Moreover, these cancer cells upon treatment with calcarea carbonica-primed T cells displayed decrease in Bcl-2 levels both at transcriptional and translational levels and thereby decreasing Bcl-2: Bax protein ratio, thus creating a pro-apoptotic environment." (PMID 24053127, 2013). "G0S2 (3.37-fold increase), which encodes a mitochondrial protein that specifically interacts with Bcl-2, is a proapoptotic factor, and its ectopic expression induces apoptosis in diverse human cancer cell lines in which endogenous G0S2 is normally epigenetically silenced." (PMID 24161199, 2013). "Mcl-1 expression renders cancer cells resistant to the Bcl-2 antagonist ABT-737." (PMID 23431463, 2013). "Elevated ratio of Bax/Bcl2 is an important marker of apoptosis in several cancer cells." (PMID 23563985, 2013). "Overexpression of antiapoptotic Bcl-2 and Bcl-xL probably occurs in more than 50% of all cancers." (PMID 24250626, 2013). "However, 14-3-3 zeta also has potential roles in cancerogenesis, based on its ability to bind NF-kappa B, beta-catenin, and Bcl-2, and to augment cancer cell proliferation." (PMID 24238270, 2013). "Moreover, the overexpression of the antiapoptotic factor BCL2 has been reported to contribute to the resistance to apoptosis induction following the short-term exposure of A549 cancer cells to 12459." (PMID 24108400, 2013). "The anti-cancer mechanisms of purple bamboo salt include the induction of apoptosis by increasing the number of apoptotic bodies and by regulating the expression levels of the apoptosis-related Bax and Bcl-2 mRNA and proteins." (PMID 23403521, 2013). "Both Beclin 1 and BCL-2 have established roles in the development of cancer." (PMID 23840208, 2013). "We found that fucoxanthin pretreatment attenuated cisplatin-induced DNA-binding activity of NFκB, restored cisplatin-inhibited IκB-α-phosphorylation, and increased the ratio of Bax/Bcl-2 mRNA expression, rendering cancer cells sensitive to apoptosis induced by cisplatin." (PMID 23299493, 2013). "Furthermore, in the pediatric pre-clinical testing program the orally bioavailable BCL-2 antagonist navitoclax (ABT-263) showed the greatest efficacy against ALL among all the cancer models tested." (PMID 23847761, 2013). "Relative levels of Bcl-2 and Beclin-1 emerged among the multiple cellular factors controlling whether autophagy contributes to cancer inhibition or survival." (PMID 23326480, 2013). "The antiapoptotic Bcl-2 proteins are widely overexpressed in human cancers including CRC." (PMID 24098503, 2013). "Since cancer cells may bypass the inhibition of one target, e.g. a reduction in BCL2 protein content can be compensated by the induction of Bcl-xL, the combined knockdown of antiapoptotic genes may be more suitable for BCa therapy." (PMID 22797576, 2012).
cancer (continued). "Moreover, Bcl-2 S-denitrosylation facilitates its ubiquitin-proteasome degradation, then initiates the activation of caspase signal pathway and finally results in cancer cell apoptosis." (PMID 22629368, 2012). "Bax/Bcl-2 may have an effect on caspase-3 by enhancing apoptosis of cancer cells by cytochrome c, APAF-1, caspase-9 and other death substrates." (PMID 22266878, 2012). "RT-PCR and Western blot were used to detect expression of NDRG2, Bcl-2 and Bax in cancer cells." (PMID 22920753, 2012). "Under basal condition, Bcl-2 S-nitrosylation prevents it from ubiquitin degradation, which forms heterodimers with the proapoptotic protein Bax to neutralize its death effector properties and switch cancer cell to survival." (PMID 22629368, 2012). "The downregulation of Bcl-2 or other anti-apoptotic proteins, such as Bcl-xL, could either induce apoptosis in cancer cells or could sensitize these cells for chemotherapy." (PMID 22424291, 2012). "However, the precise mechanism by which MDA-7IL-24 efficiently induces Bcl-2 decrease and cancer cell apoptosis remains to be defined." (PMID 22629368, 2012). "iNOS-siRNA facilitates Bcl-2 S-denitrosylation and ubiquitin-degradation, whereas the TrxR1 inhibitor auranofin prevents Bcl-2 from denitrosylation and ubiquitination, thus restrains the caspase signal pathway activation and subsequent cancer cell apoptosis." (PMID 22629368, 2012). "ABT-737, a Bad-like BH3 mimetic which selectively bounds to Bcl-2, Bcl-XL and Bcl-w, is highlighted as a promising anti-cancer agent, meanwhile, its low affinity with Mcl-1 and high basal level of Mcl-1 expression in cancer cells is preventing it from being efficient as a single agent." (PMID 23284992, 2012). "Based on the fact that anti-apoptotic proteins, Bcl-2 and Bcl-xl, are upregulated in a number of tumors, antisense oligonucleotides directed to the mRNAs of these proteins have been therapeutically used in many cancers." (PMID 22848504, 2012). "The downregulation of Bcl-2 or other antiapoptotic proteins could either induce apoptosis in cancer cells or sensitize these cells to chemotherapy." (PMID 22424291, 2012). "Because anti-apoptotic proteins could enable the radio resistance of the cancer cells, we investigated whether the expression of Bcl-2 and Bcl-xL, important proteins involved in apoptosis, were altered in the MDA-MB-231R cells." (PMID 23259599, 2012). "Berberine has been shown to suppress cancer cell growth and proliferation by inducing cell cycle arrest, stimulate cancer cell caspase-dependent apoptosis, reduce Bcl-2 and Bcl-xL levels and increase Bax and Bak levels, and inhibit metastasis by downregulating matrix metalloproteinases." (PMID 22574158, 2012). "As expected, we observed that bcl-2 mediated resistance to this compound providing evidence for the importance of the mitochondrial pathway of apoptosis for arsenic trioxide’s cytotoxicity towards cancer cells." (PMID 22590507, 2012). "Furthermore, it has been reported that Bcl-2 directly binds to COX to promote survival of cancer cells by maintaining a slight pro-oxidant state through elevated mitochondrial respiration during basal conditions." (PMID 22748147, 2012). "B-cell leukemia-lymphoma gene 2 (Bcl-2)/oblimersen for cancer." (PMID 22989709, 2012). "We proposed that targeting the overexpression of Bcl-2 and Bcl-xL may be an effective way to overcome the acquired radioresistance of cancer cells." (PMID 23259599, 2012).
cancer (continued). "Thus, VDAC1-based peptides, targeting the anti-apoptotic activity of Bcl-xL and Bcl2, can serve as potential cancer therapeutics." (PMID 23233904, 2012). "In order to further detect the role of TrxR1 in IL-24-coupled Bcl-2 S-denitrosylation, we treated these three cancer cells with TrxR1 inhibitor auranofin to detect the alterations of TrxR1 expression, Bcl-2 expression, Bcl-2 S-nitrosylation, and Bcl-2 ubiquitination." (PMID 22629368, 2012). "Moreover, the overexpression of Bcl-2 reduces the lifespan of cultured human fibroblasts as well as induces cellular senescence in human carcinoma cells." (PMID 22899934, 2012). "The cellular response of cancer cells to MiTMABs appeared to correlate with expression of Bcl-2." (PMID 21708043, 2011). "Therefore, we analysed the expression levels of three anti-apoptotic Bcl-2 family members, Bcl-2, Bcl-XL and Mcl-1, in all five cancer cell lines." (PMID 21708043, 2011). "bcl-2 staining was observed in the cytoplasm and cytomembrane of carcinoma cells." (PMID 22216342, 2011). "The conformational change of Bcl-2 may be the new mechanism explaining arsenic trioxide-induced apoptosis, other than the ones affecting the total Bcl-2 expression in some cancer cells." (PMID 20403207, 2010). "Recent researches have demonstrated that Bcl-2 could manifest opposing phenotypes, induced by interactions with proteins, such as Nur77, suggesting novel strategies for regulating apoptosis in cancers and other diseases." (PMID 20403207, 2010). "However, in cancer cells, whereas some reports show evidence for post-transcriptional down-regulation of BCL-2, others demonstrate an overproduction of the Bcl-2 protein on the basis on increased BCL-2 mRNA levels." (PMID 24281071, 2010). "For example, it could be that genes specific to common cancer-related pathways are those that are well studied, such as BCL2 or ESR2." (PMID 20459635, 2010). "Bcl-2 is a pivotal regulator of apoptotic cell death, and it is overexpressed in many cancers." (PMID 21304176, 2010). "Hence, Bcl-2 antigens appear to be a very attactrive target for anti-cancer immunotherapy both in hematopoetic and solid cancers." (PMID 21304176, 2010). "Consequently, the Bcl-2 protein is an attractive target for drug design and Bcl-2 specific antisense oligonucleotides or small molecule Bcl-2 inhibitors have shown broad anti-cancer activities in pre-clinical models and are currently in clinical testing." (PMID 21304176, 2010). "The conformational change of Bcl-2 may be a novel described mechanism of arsenic trioxide-induced apoptosis in cancer cells." (PMID 20403207, 2010). "Although regulation of apoptotic pathways has been implicated in resistance of many cancers to chemotherapy, we show that human MM lines endogenously overexpress many prosurvival genes (BCL2, cFOS, MET, etc.)in comparison to nontransformed mesothelial cells." (PMID 21159167, 2010). "The regulation of Bcl-2 by Hh signaling has been shown in several other cancer cells." (PMID 19742123, 2009). "To confirm our hypothesis that pre-treatment of PC-3 cells with P529 might reduce radiation resistance of cancer cells, we analysed p-Akt, total Akt, Bcl-2, and Bax protein levels after individual or combined treatments." (PMID 19240717, 2009).
cancer (continued). "Over expression of bcl-2 turns cells suffering from irreversible gene mutation to normal cell cycle rather than apoptosis, thereby causing cancer." (PMID 19594888, 2009). "Notably, NPC cells consistently harbor EBV DNA and express EBV proteins, LMP1 and BARF1; these proteins stimulate oncogenic antiapoptotic Bcl-2 proteins to protect host cancer cells from apoptosis." (PMID 19698176, 2009). "Overexpression of the BCL-2 protein has been frequently observed in many cancers including ALL." (PMID 19724645, 2009). "Screening of several key proteins controlling cell cycle, development, metabolism, apoptosis and growth, including Erk, Akt, GSK3β, p16 and p14, Bcl-2, c-Myc, Nestin and Sox2, showed that downregulation of Bmi1 reduced GSK3β protein levels and induced differentiation in cancer cells." (PMID 19823589, 2009). "Therefore the expression of survivin in cooperation with Bcl-2 is a significant prognostic parameter and a new therapeutic target in cancer." (PMID 19330074, 2008). "Cancer is a dynamic multi-step, multi-mechanism disease involving complex interactive and redundant pathways, e.g. upregulation of survival pathways (e.g. bcl2, NFkB, AKT and receptor kinases) and genetic and epigenetic changes in relevant targets during cancer progression." (PMID 19787092, 2008). "Additionally high expression level of anti-apoptotic Bcl-2 proteins confers a clinically important chemoresistant phenotype on cancer cells." (PMID 18454859, 2008). "Thus, Bcl-2 is a highly attractive target for the development of novel molecular therapy for the treatment of human cancer." (PMID 18803879, 2008). "ANT1 overexpression could be broadly applied for therapy to decrease Bcl-2 levels or inhibit NF-κB activity in various human cancers." (PMID 18522758, 2008). "Therefore, to bypass cancer cell survival with a Bcl-2 antagonist, neutralizing Mcl-1 appears to be critical in certain tumour environments." (PMID 19079626, 2008). "Therefore, the Bcl-2 signaling pathway is necessary for the survival of stem cells, especially cancer stem cells, because of the overexpression of Bcl-2 in cancer cells." (PMID 18803879, 2008). "It induces Bcl-2 phosphorylation and apoptosis in endothelial and cancer epithelial cells." (PMID 17426705, 2007). "However, others have reported that COX-2 inhibitors can induce apoptosis in cancer cells independently of Bcl-2." (PMID 17612393, 2007). "Recent reports that cyclooxygenase-2 (COX-2) inhibitors could induce apoptosis through Bcl-2 downregulation led us to consider the role of COX-2 inhibitors in the E1A-induced apoptosis of cancer cells." (PMID 17612393, 2007). "Bcl-2-positive carcinomas were more likely to have lower proliferation (P=0.001)." (PMID 17285125, 2007). "Although not directly linked to cancer, this receptor has been shown to interact with bcl-2, a central anti-apoptotic protein whose expression is high in both AML and ALL patients, possibly allowing its insertion to the mitochondrial outer membrane." (PMID 16842618, 2006). "Instead, we observed down-regulation of the cancer-promoting BCL2 gene." (PMID 16982006, 2006). "The bcl-2 immunostaining was found in the cytoplasm of cancer cells." (PMID 16911782, 2006). "This strategy could be used to reduce the expression of bcl-2 or bcl-XL in cancers that are predicted to be radioresistant." (PMID 15928664, 2005). "In our study, 66.7% of the carcinomas expressing PDGFR-α present Bcl2 co-expression, and we speculate that PDGFR-α might be activating anti-apoptotic routes such as the Bcl2 pathway." (PMID 16168125, 2005). "Indeed, dysregulation of BCL-2 gene family expression is common in most cancers, although the mechanisms are unclear." (PMID 12865934, 2003).